IL1B (interleukin 1 beta)
Diseases named in the same sentence as IL1B in open-access papers (continued):
Sharing a sentence is not in itself a finding about the gene and the disease.
osteoarthritis (continued). "The use of specific NF-κB inhibitors has been reported to alleviate the aggravation of IL-1β–induced osteoarthritis in mice and rats." (PMID 35795554, 2022). "It was shown that ribosome protein translation activity was increased in human osteoarthritis chondrocytes, in a rat model for traumatic osteoarthritis, and in an IL-1β-dependent in-vitro chondrocyte model for osteoarthritis." (PMID 34750309, 2022). "Accordingly, the ELISA data further confirmed the elevated protein expression of IL-1β in the serum and arthrosis of Pol β+/−-CIA mice and Pol βR137Q-CIA mice." (PMID 35794098, 2022). "Studies showed that glycyrrhizin treatment suppressed IL-1β-induced NF-κB phosphorylation in a mouse model of osteoarthritis (OA), significantly reducing IL-6, prostaglandin E2 (PGE2), nitric oxide (NO) and TNF-α levels." (PMID 35684415, 2022). "Nesfatin-1 ameliorates osteoarthritis in a rat model and suppresses cartilage matrix destruction, inflammation, and apoptosis in IL-1β-induced chondrocytes." (PMID 36008865, 2022). "Interleukin-1β (IL-1β)-induced osteoarthritis in vitro model has been widely recognized in the corresponding research field." (PMID 35935815, 2022). "A review of mechanical loading on osteoarthritis showed that mechanical load activated multiple inflammatory pathways, such as IL-1β, TNF-α, inducing chondrocyte apoptosis, synovial inflammation and subchondral bone dysfunction, finally leading to OA." (PMID 36246900, 2022). "Osteoarthritis is complex and the strategy of targeting singular pro-inflammatory markers (most notably IL-1β) to tackle the disease, at least systemically, has been recognized as ineffective." (PMID 35359946, 2022). "On a separate note, IL-1β activated Nampt expressions were previously indicated to retard articular chondrocyte differentiation and augment osteoarthritis development." (PMID 34967693, 2022). "In an in vitro cartilage degradation model of osteoarthritis, β-myrcene reduced iNOS and IL-1β and also mitigated inflammatory response in UVB-induced human skin photo-aging." (PMID 36557879, 2022). "Factors thought to drive KDM6B upregulation in damaged cartilage in osteoarthritis include IL-1β and TGF-β, both of which were shown to induce KDM6B expression in cultured human articular chondrocytes (HACs)." (PMID 35915507, 2022). "MiR-671 mimics ameliorated IL-1β-induced proliferation inhibition and apoptosis stimulation and alleviated the progression of osteoarthritis in mice." (PMID 35397550, 2022). "It is widely acknowledged that IL-1β is a crucial inflammatory mediator corresponding to osteoarthritis severity." (PMID 36466156, 2022). "Similar reports in osteoarthritis indicated that overexpressing Nr4a3 activated IL-1β-induced NF-κB, and that downregulating Nr4a3 significantly inhibited IL-1β-induced NF-κB." (PMID 35922863, 2022). "Inflammatory responses in IL-1β-stimulated human osteoarthritis chondrocytes were also suppressed by oridonin." (PMID 35469348, 2022). "The expression levels of TCA1, TLR7, MMP9, CXCL10, CXCL13, HLA-DRA, and ADIPOQSPP1 were significantly higher in the IL-1β-induced group than in the osteoarthritis group in an in vitro qPCR experiment." (PMID 35734177, 2022). "Meanwhile, sauchinone suppresses the inflammatory response in IL-1β-stimulated human chondrocytes by inhibiting the expression of NF-κB signaling pathway components, thereby reducing osteoarthritis." (PMID 36699607, 2022). "Secondly, we observed that LMX1B silence promoted cell survival and proliferation and suppressed cell apoptosis and inflammatory response in IL-1β-induced human osteoarthritis chondrocytes." (PMID 36133743, 2022). "Inflammatory mediators, like, IL-6, IL-1β, among several other factors play a crucial role in the pathogenesis of osteoarthritis." (PMID 35600853, 2022). "IL-1β -induced preferential translation of osteoarthritis-related proteins in chondrocytes was suggested to be mediated by their 5′ untranslated regions." (PMID 34750309, 2022).
osteoarthritis (continued). "Ligand binding of NGF to TrkA activates transcriptional and posttranscriptional pathways that mediate IL-1β release, while IL-1β induces chondrocyte inflammation and osteoarthritis via the NF-κB signaling pathway." (PMID 36292950, 2022). "In the current study, we determined the specific role of LMX1B on cell apoptosis and inflammatory response in IL-1β-induced human osteoarthritis chondrocytes." (PMID 36133743, 2022). "The levels of serum myostatin and interleukin (IL)-1β were significantly elevated in synovial fluid from RA patients than that from osteoarthritis patients, immunohistochemistry data also revealed a positive correlation between myostatin and IL-1β, TNF-α." (PMID 36330524, 2022). "Significantly increased IL-1β in synovium of patients with osteoarthritis can strongly activate C-Jun, P38 MAPKs, and ERKs through IL-1R." (PMID 35847580, 2022). "It has been found that the expression of microRNA-138 increases in patients with osteoarthritis; therefore, the interaction between this microRNA with the IL-1β gene destroys the extracellular matrix of cartilage in OA patients." (PMID 35782767, 2022). "This study aims to investigate the effects of Icariin (ICA) on interleukin-1β (IL-1β)-induced osteoarthritis (OA) and its potential mechanism of action." (PMID 36253872, 2022). "In our cell culture model, the two pro-inflammatory cytokines, IL-1β and IL-17, were used to trigger inflammation, mimicking osteoarthritis." (PMID 35885038, 2022). "Inspired by oxidative stress in the pathogenesis of osteoarthritis, we firstly testified the antioxidant capacity of a synthetic small molecule compound, oltipraz (OL), to the chondrocytes treated by IL-1β." (PMID 36123746, 2022). "IL-1β, as a major driver of osteoarthritis progression, is recognized to induce chondrocytes apoptosis in osteoarthritic cartilage." (PMID 36032700, 2022). "A recent study indicates that byakangelicin inhibits IL-1β-induced mouse chondrocyte inflammation in vitro and ameliorates murine osteoarthritis in vivo." (PMID 35656472, 2022). "With the continuous development of studies on cartilage-derived diseases such as traumatic epiphyseal plate closure and osteoarthritis, increasing attention is being gained to IL-1β action." (PMID 36575508, 2022). "All osteoarthritis parameters including IL-1β, caspase 3 and MMP-9 were significantly increased in the obese group compared to control." (PMID 36097281, 2022). "The pro-inflammatory cytokine IL-1β is one of the central pro-inflammatory cytokines in many diseases and activates various pathways leading to the progression of osteoarthritis." (PMID 35885038, 2022). "In IL-1β-stimulated osteoarthritis, the inhibitory effect of SNHG5 on the apoptosis of chondrocytes and inflammation is offset by silencing TGFBR3." (PMID 36180862, 2022). "For instance, administering mice with anemonin attenuated osteoarthritis progression via inhibiting IL-1β activation." (PMID 35346284, 2022). "IL-1β, a major inflammatory and catabolic cytokine in the pathophysiology of osteoarthritis, has been widely used to research." (PMID 36238555, 2022). "SA alleviated the progression of osteoarthritis (OA) by reducing the levels of IL-1β, IL-6, prostaglandin E2 (PGE2), nitric oxide (NO), and TNF-α in vitro." (PMID 35204088, 2022). "One of which was carried out on IL-1β-stimulated chondrocytes to identify the potential biological processes in the progression of osteoarthritis." (PMID 35573252, 2022). "The presence of IL-1β in the joint synovium of patients with RA or osteoarthritis (OA) plays a key role in cartilage destruction." (PMID 36077525, 2022). "A large number of inflammatory mediators including IL-6, TNF-α and IL-1β were detected in osteoarthritis." (PMID 35563622, 2022). "Recent studies showed that interleukin-1β (IL-1β), a key catabolic cytokine can induce O-GlcNAc accumulation in osteoarthritis." (PMID 36032089, 2022).
osteoarthritis (continued). "In osteoarthritis, IL-1β expression was shown to increase in conjunction with decreased extracellular matrix formation by chondrocytes contributing to osteoarthritic cartilage degradation." (PMID 34831397, 2021). "Consistently, we also found that inhibition of SIRT1 attenuated FA‐mediated protective effects against IL‐1β‐induced toxicity to osteoarthritis chondrocyte." (PMID 34078001, 2021). "Consistent with previous studies, IL‐1β significantly suppressed the viability of osteoarthritis chondrocytes and co‐treatment of the chondrocytes with FA at 5 and 10 μM dose‐dependently improved cell viability in the presence of IL‐1β." (PMID 34078001, 2021). "To evaluate the anti-osteoarthritis effect of V. thapsus on IL-1β-stimulated HC, we performed a gene expression profile with specifics inflammatory mediators and MMPs after 24 h and 6 days of treatment." (PMID 34500824, 2021). "Protein expression levels of Akt, phosphorescent p-Akt, mammalian target of rapamycin (mTOR), and p-mTOR in the PI3K/Akt/mTOR signaling pathway were decreased in the IL-1β-induced SW1353 cells following scutellarein treatment of osteoarthritis." (PMID 34671661, 2021). "It has been revealed that IL-1β is the major inflammatory mediator during the osteoarthritis process." (PMID 33663609, 2021). "Luo evaluated the anti-inflammatory effect of verticine on IL-1β induced inflammatory response in mouse articular chondrocytes and ameliorates murine osteoarthritis model." (PMID 35126123, 2021). "This was consistent with our previous results that regulating IL-1β expression can improve the symptoms of osteoarthritis." (PMID 34683827, 2021). "We aimed to determine the effects of ferulic acid (FA) on IL‐1β‐induced osteoarthritis chondrocyte degeneration." (PMID 34078001, 2021). "The impact of FA on IL‐1β‐induced osteoarthritis chondrocyte toxicity was determined by prostaglandin E2 (PGE2), nitrite, IL‐6, components of the extracellular matrix, and markers of oxidative stress." (PMID 34078001, 2021). "TNF-α, together with IL-1β, IL-6, and IL-17 are also known to upregulate angiogenic substances, as seen in pathogenesis of osteoarthritis." (PMID 34172047, 2021). "Interleukin (IL)-1β is an important pro-inflammatory cytokine in the progression of osteoarthritis (OA), which impairs mitochondrial function and induces the production of nitric oxide (NO) in chondrocytes." (PMID 33804447, 2021). "As a classic arthrosis model, human primary chondrocytes were exposed to the pro-inflammatory cytokine IL1-β (1 ng/mL)." (PMID 34444810, 2021). "As a result, IL‐1β treatment of chondrocytes isolated from osteoarthritis patients has been widely used to study osteoarthritis pathogenesis and the development of therapeutic strategies." (PMID 34078001, 2021). "Taking CircRNA‐9119 as an example, its overexpression up‐regulates PTEN expression by down‐regulating microRNA‐26a to protect IL‐1β‐treated osteoarthritis‐mediated chondrocytes from apoptosis." (PMID 33733589, 2021). "ELISA analysis showed that PGE2 production was significantly elevated in osteoarthritis chondrocytes as a result of IL‐1β treatment and co‐treatment of the cells with FA significantly suppressed IL‐1β‐induced PGE2 production." (PMID 34078001, 2021). "We tested both of the lower concentrations in IL‐1β‐treated osteoarthritis chondrocytes and found FA dose‐dependently suppressed IL‐1β‐induced osteoarthritis chondrocyte degeneration." (PMID 34078001, 2021). "TQ has been reported to reduce IL-1β-induced inflammation in human osteoarthritis chondrocytes by suppressing the NF-κB and MAPK signaling pathways." (PMID 33920708, 2021). "It has been found that trace amounts of IL-1β can be found in the synovial fluid of normal joint tissues, while IL-1β is highly expressed in the synovial fluid of osteoarthritis (OA) patients, which is positively correlated with articular cartilage injury." (PMID 33430857, 2021).
osteoarthritis (continued). "According to the chondroprotective effects of ALE metabolites with regard to the IL-1β-driven stress, luteolin attenuates osteoarthritis progression and collagen II degradation in a rat model of monoiodoacetate-induced osteoarthritis." (PMID 34444810, 2021). "It has also been reported that HPT can significantly inhibit IL-1β-induced inflammatory response in human chondrocytes in osteoarthritis." (PMID 34603050, 2021). "It was reported that avocado and soybean unsaponifiables can restrain osteoarthritis through inhibition of proinflammatory cytokines such as IL-1β, IL-3, IL-6, IL-8, IL-13, and TGF-β; also, they can modulate oxidative damages by repression of ROS production." (PMID 34258301, 2021). "The beneficial results of PBA application under inflammatory conditions, such as in rat models of permanent ischemic stroke, osteoarthritis, or acute lung injury models, were shown to decrease the release of pro-inflammatory mediators IL-1β, TNFα, and IL-6." (PMID 34656124, 2021). "We found that IL‐1β significantly increased collagen I mRNA expression in osteoarthritis chondrocytes which was suppressed by FA treatment." (PMID 34078001, 2021). "Our results revealed that co‐treatment of osteoarthritis chondrocytes with FA and IL‐1β suppressed IL‐1β‐induced production of IL‐6 as well as these inflammatory mediators, indicating dampening of the inflammatory response of the cells." (PMID 34078001, 2021). "Our results indicate that FA effectively prevented IL‐1β‐induced toxicity in osteoarthritis chondrocytes." (PMID 34078001, 2021). "Sinomenine regulation miR-223-3p overexpression and blocks IL-1β-induced chondrocyte apoptosis and protects osteoarthritis." (PMID 34753389, 2021). "To investigate how FA impacted IL‐1β‐induced osteoarthritis chondrocyte degeneration, we examined chondrocyte de‐differentiation markers collagen I and Runx‐2 and chondrogenic genes including collagen II and aggrecan." (PMID 34078001, 2021). "Interleukin‐1β (IL‐1β), a cytokine produced by chondrocytes, contributes to osteoarthritis pathogenesis." (PMID 34078001, 2021). "Elevated levels of IL-1β have been reported in humans with osteoarthritis at concentrations between 0.021 to 0.146 ng/ml compared to levels up to 0.020 ng/ml in healthy subjects." (PMID 34563724, 2021). "To further investigate how FA suppressed IL‐1β‐induced osteoarthritis chondrocyte degeneration, we determined the levels of MMP production." (PMID 34078001, 2021). "At experimental level, miR-146a is highly upregulated in IL-1β treated chondrocytes, in surgically-induced osteoarthritis in animals, and in response to mechanical stress." (PMID 34066077, 2021). "We used a Sprague-Dawley (SD) rat model of CollagenaseII-induced osteoarthritis (OA) as well as IL-1β-induced OA chondrocytes." (PMID 34976968, 2021). "Osteoarthritis is accompanied with a simultaneous inflammation from early stage, and IL‐1β is one of the key inflammatory cytokines involved in the pathogenesis of the disease." (PMID 34037306, 2021). "Nog serves as an inhibitor of bone morphogenetic proteins (BMPs) and prevents cartilage degeneration and osteoarthritis development by inhibiting Il1β and Bmp2 expression." (PMID 33407721, 2021). "Human synovial MSCs-derived exosomes relieved IL-1β-induced osteoarthritis by carrying miR-129-5p into chondrocytes." (PMID 34777000, 2021). "Clinical studies confirmed that inflammatory cytokines such as TNF-α, IL-1β and IL-6 were highly expressed in osteoarthritis, which induced chondrocyte apoptosis and destroy articular cartilage." (PMID 34049522, 2021). "Further, they demonstrated that IL-1β secretion is higher in RA patients when compared to osteoarthritis (OA) individuals." (PMID 32365786, 2020).
osteoarthritis (continued). "In the genome‐wide expression analysis, 39 protein‐coding genes were found to be up‐ or down‐regulated with fold change (FC) ≥ 2.0 into either direction by the mPGES‐1 inhibitor MF63 in chondrocytes stimulated with the osteoarthritis related cytokine IL‐1β." (PMID 32449517, 2020). "Current osteoarthritis drug development efforts have focused on targeting the cytokine interleukin 1β (IL-1β), which has been shown to be an essential mediator of inflammatory signaling." (PMID 33614593, 2020). "Our data showed that FJHKO supplementation in rats with MIA induced osteoarthritis significantly decreased the expression of pro-inflammatory cytokines (IL-1β, TNF-α) and inflammatory factors compared with that in rats without FJH-KO supplementation." (PMID 33233504, 2020). "Immune cells like activated neutrophils and macrophages can secrete cytokines, such as IL-6 and IL-1β, which amplify the inflammatory process in osteoarthritis." (PMID 32189997, 2020). "Since IL-1β has been proven to play a significant role in the pathogenesis of osteoarthritis, it is commonly used to induce an in vitro osteoarthritis model in chondrocytes." (PMID 32189997, 2020). "A study conducted among patients with osteoarthritis showed that IL-1β, IL-6, IL-8, IL-18, IL-17, IL-22, and transforming growth factor-beta 1 (TGFβ1) were increased in the inflamed synovium tissues compared to the noninflamed tissues." (PMID 32189997, 2020). "Chrysin suppressed nuclear factor-κB and high-mobility group box chromosomal protein in human osteoarthritis chondrocytes stimulated by IL-1β." (PMID 33260891, 2020). "Previous studies have shown that increased IL‐1β production is closely related to a variety of diseases, including lupus arthritis, osteoarthritis and ankylosing arthritis." (PMID 33098220, 2020). "In a murine model of arthrosis following joint fracture, IL-1β was the main mediator of the acute phase of inflammation, particularly in the first 3 days." (PMID 33144846, 2020). "For example, the integral role of IL-1β in the pathogenesis of osteoarthritis can be targeted to prevent further degradation of the joint tissue." (PMID 32189997, 2020). "Osteoarthritis (OA), the most common joint disease worldwide, is characterized by low-grade inflammation and increased levels of cytokines, including IL-1β and IL-18." (PMID 33014529, 2020). "IL-1β upregulated IκBζ expression in chondrocytes, and IκBζ expression was found to be increased in cartilage tissues of patients with osteoarthritis." (PMID 32079226, 2020). "miR-497-5p was revealed to be significantly downregulated after 24 h stimulation of human primary osteoarthritis chondrocytes with IL-1β, indicating its relevance in joint disease." (PMID 33168056, 2020). "It is important to note that both TNF-α and IL-1β play an important role in the pathophysiology of osteoarthritis." (PMID 32947946, 2020). "The most potent compound, (S)-(+)-carvone, significantly decreased the expression of NOS2 and IL-1β in macrophages and in a cell model of osteoarthritis using primary human chondrocytes." (PMID 32350292, 2020). "In line with our study, miR-497-5p was downregulated in osteoarthritis cartilage, while miR-497-5p overexpression attenuated cartilage matrix degradation stimulated by IL-1β in chondrocytes." (PMID 33168056, 2020). "A chronic and low level IL-1β (25 pg/ml) treatment was used accordingly to a protocol developed in our laboratory to mimic the osteoarthritis environment on synoviocytes." (PMID 32345351, 2020). "In osteoarthritis (OA), miR-411 was repressed by IL-1β treatment in OA cartilage, directly targeted MMP-13 to inhibit chondrocyte cell proliferation, and increased expression of type II and type IV collagen." (PMID 30390072, 2019). "As part of the pathogenesis of osteoarthritis (OA), chondrocytes lose their phenotype and become hypertrophic, or dedifferentiate, mainly driven by interleukin-1β (IL-1β)." (PMID 30861996, 2019).